IGFBP7 (insulin like growth factor binding protein 7)
Diseases named in the same sentence as IGFBP7 in open-access papers (continued):
Sharing a sentence is not in itself a finding about the gene and the disease.
lung carcinoma (continued). "We found that IGFBP7 expression was significantly elevated in EGFR-TKI-resistant cells, and that high plasma IGFBP7 levels or IGFBP7 IHC-positive tumors in patients with lung cancer were correlated with shorter PFS when EGFR-TKI was used as the first-line treatment." (PMID 30609749, 2019). "The re-expression of SLIT2, MAL and IGFBP7 that was observed in lung cancer cell lines after treatment with a demethylating agent exhibited good concordance with the methylation status, suggesting that expression of those genes was downregulated mainly by hypermethylation." (PMID 23381221, 2013). "Additionally, in specific cases a relatively high change in Young’s modulus did not correspond to marked expression changes of a given gene — see for example low CAV1 changes observed in MCF10A PIK3CA mutant, or low IGFBP7 changes in intestine and lung carcinoma samples." (PMID 39960760, 2025). "Therefore, IGFBP7 may play a different role in predicting lung cancer prognosis and drug efficacy." (PMID 40224214, 2025). "In this study, we found that IGFBP7 contributes to resistance to EGFR-TKIs and showed that enhanced IGFBP7 expression promoted resistance to EGFR-TKI in lung cancer cells by mediating the IGF-1R pathway." (PMID 30609749, 2019). "Thus, IGFBP7 may be a novel target for blocking IGF-1R signaling in lung cancer cells." (PMID 30609749, 2019). "Moreover, during the progression of lung cancer, the proportion of EDN1+CCL2+cECs decreases, while the proportion of IGFBP7+PLVAP+ECs significantly increases." (PMID 37187731, 2023). "To further validate the role of IGFBP7 on the c-Fos/YAP/TEAD1/TEAD4 signaling axis in human lungs, we analyzed the expression of IGFBP7/c-Fos/YAP/TEAD1/TEAD4 in lung tissues of ARDS patients and para-cancerous tissues of lung cancer patients collected previously." (PMID 38840498, 2024). "However, the role of IGFBP-7 in lung cancer is not very clear, as other studies indicate that high serum levels of this protein correlated with a positive nodal status, and that the gene over-expression was markedly increased in AZD9291-resistant cell lines and patients." (PMID 36902237, 2023). "However, no previous studies have examined the correlation between IGFBP7 and acquired EGFR-TKI resistance in lung cancer." (PMID 30609749, 2019).
glioma (18 papers, 2010 to 2026). A benign or malignant brain and spinal cord tumor that arises from glial cells (astrocytes, oligodendrocytes, ependymal cells). "From DAVID and GSEA analysis, our results revealed that IGFBP7 expression was associated with the immune‐related pathways and NF‐κB transcription factor in glioma." (PMID 36043552, 2023). "In glioma patients, higher expressions of IGFBP7 were also associated with the worse clinical outcomes." (PMID 36043552, 2023). "It was shown that IGFBP3, IGFBP5, and IGFBP7 were highly expressed in glioma and were associated with higher tumor grade and poorer survival, consistent with our study." (PMID 35992105, 2022). "The pathways associated with IGFBP7 in glioma were further determined through GSEA assay." (PMID 36043552, 2023). "At markedly reduced intravenous doses, IGFBP7-sEVs efficiently concentrated temozolomide (TMZ) within glioma and elicited pronounced tumor growth inhibition." (PMID 41566763, 2026). "Our data suggest that IGFBP7-modified sEVs represent a novel platform that enables highly efficient, glioma VECs-targeted delivery of therapeutics into glioma, and are adaptable to a broad spectrum of agents, especially immunomodulators." (PMID 41566763, 2026). "To delve deeper into the connection between IGFBP7, FOSL2, the IGFBP7 Risk Score (IGRS), and glioma, we require extensive sample sizes and collaboration with multiple research centers." (PMID 39403379, 2024). "Secondly, we have only done scrna-seq and bulk RNA-seq analyses and in vitro experiments, and we need large sample and multi-center research to further explore the relationship between IGFBP7, FOSL2, the IGFBP7 Risk Score (IGRS), and glioma." (PMID 39403379, 2024). "To assess the role of the C0 IGFBP7+ glioma cell subgroup in neuroglioma progression, we performed univariate Cox and LASSO regression analyses on candidate genes, identifying four genes strongly linked to prognosis." (PMID 39403379, 2024). "In order to better serve the clinic, we evaluated the prognostic characteristics of the C0 IGFBP7+ Glioma cell subgroup identified in this study." (PMID 39403379, 2024). "The results showed that C0 IGFBP7+ Glioma cells had the highest cell stemness among the seven subclusters, and C2 LINC02283+ Glioma cells had the highest G2M.Score." (PMID 39403379, 2024). "This was consistent with the previous results of CytoTRACE analysis and monocle 2 pseudotime analysis that C0 IGFBP7+ Glioma cells were at the end of differentiation and had high cell stemness, with most of the C0 subclusters distributed in subgroup IV." (PMID 39403379, 2024). "The findings indicated that the enhanced pathways in C0 IGFBP7+ Glioma cells included inhibiting hydrolase activity, promoting cell-substrate adhesion, aiding in wound healing, inhibiting peptidase activity, and regulating cell-substrate adhesion." (PMID 39403379, 2024). "Our exploration of the astrocyte tumor microenvironment highlighted the critical role of the C0 IGFBP7+ glioma subpopulation in astrocytoma progression." (PMID 39403379, 2024). "CytoTRACE and Monocle 2 analyses suggested that C0 IGFBP7+ glioma cells were likely at advanced stages of differentiation with high differentiation potential." (PMID 39403379, 2024). "Studies have reported that IGFBP7 promotes the proliferation, differentiation, and migration of glioma cells, keratinocyte, and bone marrow mesenchymal stem cells and participates in exercise-triggered myocyte protection, thereby improving myocyte function." (PMID 38840498, 2024). "We further discussed the relationship between IGFBP7 Risk Score (IGRS) and the immune microenvironment of glioma and analyzed the tumor immune infiltration of the two groups based on High IGRS Group and Low IGRS Group." (PMID 39403379, 2024). "According to the score, we divided the C0 IGFBP7+ Glioma cell subgroup into High IGRS Group and Low IGRS Group, and further analyzed the high and low IGRS Groups." (PMID 39403379, 2024).
glioma (continued). "The transcription factor FOSL2 was most distributed in the C0 IGFBP7+ Glioma cells subgroup, and the distribution in other subgroups was different, with statistical differences." (PMID 39403379, 2024). "The analysis of the current study revealed that C0 IGFBP7+ Glioma cells were a noteworthy subpopulation of astrocytoma, influencing the differentiation and progression of astrocytoma." (PMID 39403379, 2024). "Glioma patients with IGFBP7 lower expressions had prolonged overall survival compared with glioma patients with IGFBP7 higher expressions in TCGA‐GBMLGG, CCGA‐GBMLGG, GSE4412 ‐GBMLGG and GSE43378 ‐GBMLGG datasets." (PMID 36043552, 2023). "Through analysis of the DNA amplification, gene expression, DNA methylation of IGFBP7, our results suggested that compared with other genes in 4q12 amplicon, IGFBP7 served as ideal prognostic marker of glioma." (PMID 36043552, 2023). "Using DAVID online annotation, functional relevance of IGFBP7 correlated genes in glioma was determined." (PMID 36043552, 2023). "The stromal and immune scores were also correlated with IGFBP7 in glioma patients, particular in LGG patients." (PMID 36043552, 2023). "Overall, IGFBP7 amplification, IGFBP7 hypo‐methylation and IDH mutation were combined to contribute to the malignant roles of IGFBP7 in glioma." (PMID 36043552, 2023). "They reported that IGFBP7 expression at the mRNA level was downregulated in glioma compared to normal brain tissue." (PMID 37660019, 2023). "The alterations of IGFBP7 methylation in glioma were also contributing to the unfavorable prognostic significance of IGFBP7." (PMID 36043552, 2023). "To further demonstrate the functions of IGFBP7, we identified the differentially expressed genes between IGFBP7 highly expressed and lowly expressed glioma in TCGA and CGGA datasets." (PMID 36043552, 2023). "Except gain of DNA copy number, altered DNA methylation of IGFBP7 was also contributing to the unfavorable prognostic effects of IGFBP7 in glioma." (PMID 36043552, 2023). "It has been previously reported that insulin-like growth factor binding protein 7 (IGFBP-7) regulates the migration of glioma cells through the AKT-ERK pathway, thereby playing an important role in the growth and migration of gliomas." (PMID 34970298, 2021). "This group also found that IGFBP7 mediates glioma cell growth and cell migration through the regulation of AKT and ERK1/2 activation." (PMID 32500027, 2020). "IGFBP7 was found highly expressed in the vessels of glioma; it can interact with extracellular matrix protein to induce the adhesion and migration of endothelial cells." (PMID 24427302, 2014). "For example IGFBP7 also binds directly to insulin and in an artificial cell system it was recently demonstrated that glioma cell growth can be mediated by expressing IGFBP7." (PMID 21943323, 2011). "Furthermore, in the PTN signaling pathway network, the C0 IGFBP7+ Glioma cells subcluster showed greater importance as a sender, receiver, mediator, and influencer when compared to other types of cells." (PMID 39403379, 2024). "We analyzed the TOP1 transcription factor FOSL2 of the C0 IGFBP7+ Glioma cells subgroup, which may be at the end of differentiation." (PMID 39403379, 2024). "IGFBP7 over‐expression was correlated with the unfavorable outcomes of glioma." (PMID 36043552, 2023). "All those results highlighted the correlations of IGFBP7 and immune infiltration of glioma." (PMID 36043552, 2023). "Moreover, the Kaplan–Meier survival analysis validated the unfavorable prognostic effects of IGFBP7 in glioma." (PMID 36043552, 2023). "Moreover, IGFBP7 was a prognostic biomarker of glioma and IGFBP7 was correlated with the overall survival of glioma in TCGA‐GBMLGG, CCGA‐GBMLGG, GSE4412‐GBMLGG and GSE43378‐GBMLGG four independent glioma cohorts." (PMID 36043552, 2023).
glioma (continued). "Contrast with the previous results that IGFBP7 lower expression was correlated with the unfavorable prognosis of glioma, our results demonstrated that IGFBP7 was over‐expressed in GBM and higher expression of IGFBP7 was correlated with the unfavorable prognosis of GBM." (PMID 36043552, 2023). "IGFBP7 was higher in glioma patients with wild type IDH or with higher grades." (PMID 36043552, 2023). "The IGFBP7 expression levels in different grades of glioma were also tested." (PMID 36043552, 2023). "Next, we tested the correlations of IGFBP7 and immune infiltration of glioma." (PMID 36043552, 2023). "So, compared with PDGFRA, IGFBP7 was a more suitable prognostic and therapeutic target of glioma." (PMID 36043552, 2023). "Also the relationships between IGFBP7 and immune microenvironment of glioma were needed further studies." (PMID 36043552, 2023). "Next, large glioma cohorts should be further studied to confirm the prognostic roles of IGFBP7." (PMID 36043552, 2023). "Among all those genes, IGFBP7 was particularly over‐expressed in glioma tissues." (PMID 36043552, 2023). "At last, we showed the prognosis of IGFBP7 methylation in glioma." (PMID 36043552, 2023). "Similarly, IGFBP7 hyper‐methylated glioma had higher clinical overall survival compared with IGFBP7 hypo‐methylated glioma in TCGA‐GBMLGG and CGGA‐GBMLGG datasets." (PMID 36043552, 2023). "Furthermore, IGFBP7 expression correlated well with tumor grade and low overall glioma patient survival." (PMID 32500027, 2020). "The results showed that most of the astrocytoma subclusters had a higher percentage of G1 cell cycle, in addition, C0 IGFBP7+ Glioma cells and C4 MX1+ Glioma cells had a higher percentage of Group IV, suggesting that the malignant degree of cells in these two subclusters might be higher." (PMID 39403379, 2024). "IGFBP7 could influence the immune microenvironment of glioma." (PMID 36043552, 2023). "Moreover, IGFBP7 was over‐expressed in glioma patients with wild type IDH or with high grades." (PMID 36043552, 2023). "Furthermore, IGFBP7 was correlated with the immune infiltrations of glioma." (PMID 36043552, 2023). "And in PDGFRA driven glioma, inhibition of IGFBP7 may improve the efficacy of PDGFRA inhibitors." (PMID 36043552, 2023). "However, the prognosis of PDGFRA and IGFBP7 in glioma is unclear." (PMID 36043552, 2023). "Moreover, IGFBP7 which acts through autocrine/paracrine pathways to inhibit BRAF-MEK-ERK signaling and induce apoptosis, but it is contradictory to some researcher's findings, as they indicated that IGFBP7 was highly overexpressed in glioma tissues, mediateing glioma cell growth, and migration." (PMID 20158915, 2010). "A subgroup of glioma carry genetic 4q12 amplification including platelet derived growth factor receptor α (PDGFRA) and insulin like growth factor binding protein 7 (IGFBP7)." (PMID 36043552, 2023). "More metastasis biomarkers such as TGM2, GBP1 and IGFBP7 were checked too, and all of their expressions have a positive correlation with the expression in CAV1 in all different types of gliomas." (PMID 37642765, 2023). "We classified the 40,650 astrocytomas obtained by Seurat and named the seven subclusters according to the marker genes as C0 IGFBP7+ Glioma cells, C1 OLIG2+ Glioma cells, C2 LINC02283+ Glioma cells, C3 LINC00632+ Glioma cells, C4 MX1+ Glioma cells, C5 FOSB+ Glioma cells, and C6 DLL3+ Glioma cells." (PMID 39403379, 2024). "However, the expression and prognosis of KIT, CHIC2, EXOC1, IGFBP7, RASL11B or USP46 in glioma are unclear." (PMID 36043552, 2023). "In lower grade glioma (LGG), PDGFRA over‐expression was not correlated with the unfavorable prognosis of LGG, while, IGFBP7 was a prognostic biomarker of LGG." (PMID 36043552, 2023).
glioma (continued). "As lower-grade glioma tissue sections do not express IGFBP7 (D Stanimirovic, unpublished observations), anti-IGFBP7 sdAb may feasibly represent a useful follow-up molecular imaging tool in determining when the ‘angiogenic switch’ has been turned on for low-grade gliomas." (PMID 20959824, 2010). "IGFBP7 but not PDGFRA served an ideal prognostic marker and therapeutic target of glioma." (PMID 36043552, 2023).
liver fibrosis (18 papers, 2016 to 2025). "Ultimately, THBS1 and IGFBP7 were selected as key genes associated with liver fibrosis and T2DM." (PMID 40299397, 2025). "Validation confirmed that THBS1 was upregulated in both conditions, while IGFBP7 was mainly elevated in liver fibrosis." (PMID 40299397, 2025). "Median IGFBP7 at baseline was higher in the group who developed liver fibrosis according to ELF ≥ 9.8 at follow‐up compared to the group with ELF remaining < 9.8 at follow‐up (220.0 [IQR: 207.6–243.6] vs. 192.8 [IQR: 173.3–207.9] [p = 0.001])." (PMID 40552595, 2025). "In contrast, the expression levels of IGFBP7 were upregulated in liver fibrosis patients but remained unchanged in T2DM patients." (PMID 40299397, 2025). "The inhibitory effect of anti-IGFBP7 antibody on activated HSCs provides a promising intervention for liver fibrosis." (PMID 26974954, 2016). "Moreover, we showed that IGFBP7 serum levels at baseline can predict new onset liver fibrosis over time, defined as ELF ≥ 9.8 at follow‐up in participants with ELF < 9.8 at baseline, with good diagnostic accuracy (AUC 0.79)." (PMID 40552595, 2025). "The expression of IGFBP-7 is significantly elevated in liver biopsies from patients with fibrosis and cirrhosis, whereas the inhibition or silencing of this protein prevents the accumulation of an extracellular matrix in experimental models of liver fibrosis." (PMID 38541155, 2024). "Moreover, through the regulation of MMPs/TIMPs balance, SHH pathway mediates IGFBP-7 knockdown-induced attenuation of hepatic fibrosis." (PMID 34905501, 2021). "Furthermore, several lncRNAs target genes that have been reported to associated with HSC activated and liver fibrosis, such as CTGF, FGF2, FGFR1, IGFBP7 and NTN4." (PMID 29495545, 2018). "A recent analysis identified a potential link between IGFBP-7 and hepatic fibrosis." (PMID 27769173, 2016). "IGFBP7 knockout significantly decreased lipid accumulation, inflammation, and liver fibrosis, whereas liver-specific IGFBP7 overexpression dramatically exacerbated liver fibrosis in the zebrafish NAFLD model, suggesting that IGFBP7 may act as an important regulator in NAFLD progression." (PMID 39045455, 2024). "The aim of this study was to investigate liver steatosis and the potential for liver fibrosis development in patients with newly diagnosed acromegaly, using QUS techniques (TAI and SWE) and biochemical markers (CK18 and IGFBP7)." (PMID 38709454, 2024). "In the context of liver fibrosis in MASLD, IGFBP7 contributes to fibrogenesis by playing a role in the activation and transdifferentiation of hepatic stellate cells." (PMID 38811591, 2024). "In particular, it has been demonstrated a mutual regulation between IGFBP-7 and TGF-β in hepatic stellate cells which most likely accelerates the progression of liver fibrosis." (PMID 34905501, 2021).